CD68 (CD68 molecule)
Diseases named in the same sentence as CD68 in open-access papers (continued):
Sharing a sentence is not in itself a finding about the gene and the disease.
Langerhans cell histiocytosis (28 papers, 2015 to 2026). Langerhans cell histiocytosis (LCH) is a systemic disease associated with the proliferation and accumulation (usually in granulomas) of Langerhans cells in various tissues. "Erdheim-Chester disease is a multisystem non-Langerhans cell histiocytosis with fibrosis characterized by CD68+, CD1a-, and S100- expression." (PMID 40351997, 2025). "This immunoprofile helps distinguish them from mimics such as lipomas, mucosal prolapse, signet-ring cell carcinoma, and other conditions positive for both CD68 and S100, like Langerhans cell histiocytosis and dendritic cell tumor." (PMID 40693216, 2025). "The IHC profile confirmed the diagnosis, showing the characteristic S‐100+/CD68+/Langerin‐ phenotype, which helps distinguish it from Langerhans cell histiocytosis (LCH)." (PMID 41425519, 2025). "Erdheim-Chester disease (ECD) is an ultra-rare non-Langerhans cell histiocytosis characterized by CD68-positive, CD1a/S100-negative histiocytes, frequently associated with BRAF V600E and MAPK pathway mutations." (PMID 41497010, 2025). "The cells were positive for Langerin, CD1a, S100, and CD68 immunostains, consistent with cutaneous Langerhans cell histiocytosis." (PMID 36619508, 2022). "Langerhans cell histiocytosis was confirmed by neuroendoscopic procedures, and immunohistochemical staining showed that all cases (7/7) were positive for CD68, CD1a, Langerin, and S-100." (PMID 27760550, 2016). "Erdheim–Chester disease (ECD) is a rare, multiorgan, non-Langerhans cell histiocytosis of uncertain origin, characterized by systemic xanthogranulomatous infiltration from CD68+CD1a- histiocytes." (PMID 26512552, 2015). "Langerhans cell histiocytosis is characteristically positive for langerin, CD1a, and S100 and may show variable or dot-like positivity for CD68." (PMID 40398847, 2025). "Diagnosis of ECD requires typing of histiocytes in tissues: these are typically foamy and CD68+ CD1a− in ECD, whereas in Langerhans cell histiocytosis (LCH), they are CD68+ CD1a+." (PMID 34360745, 2021). "Additionally BRAFV600E mutation was also detected in other two rare histiocytoses: Langerhans-cell histiocytosis (LCH) and Erdheim-Chester disease (ECD) characterized by a phenotype similar to CD1a+ S100+ Langerhans cells and foamy CD68+, CD1a- S100- histiocytes, respectively." (PMID 27738305, 2017). "Langerhans cell histiocytosis (LCH) is a neoplastic transformation of myeloid precursors characterized by the expression of CD1a, CD68, CD207 (Langerin), and S-100." (PMID 37522932, 2023). "Immunohistochemistry aids in distinguishing RDD from other histiocytic disorders; RDD cells are typically positive for S-100 and CD68 and negative for CD1a, unlike Langerhans cell histiocytosis." (PMID 40656404, 2025). "In langerhans cell histiocytosis, CD1a, CD207 (langerin), S100, CD68, and HLA-DR were positive." (PMID 39850815, 2024). "Mononuclear cells of the interstitium in the kidney biopsy showed positivity for CD68 (histiocyte), and the biopsy was negative for S100 protein which ruled out Langerhans cell histiocytosis (LCH)." (PMID 36978015, 2023). "And negative expression of IHC staining of CD68 ruled out the diagnosis of Langerhans cell histiocytosis." (PMID 30621651, 2019). "Erdheim Chester disease (ECD) is a rare, non-Langerhans cell histiocytosis characterized by widespread tissue infiltration by CD68-positive, CD1a-negative foamy histiocytes." (PMID 30474563, 2018). "Rosai–Dorfman disease (RDD) is a rare form of non-Langerhans cell histiocytosis (non-LCH) that is characterized by the accumulation of large pale CD68+, S100+, and CD1a− histiocytes in various tissues and organs with a spectrum of clinical manifestations." (PMID 38769536, 2024).
Langerhans cell histiocytosis (continued). "In the last decade, the gain-of-function BRAFV600E mutation was observed to be recurrent in the histiocytic disorders Langerhans cell histiocytosis (LCH) and Erdheim-Chester disease (ECD), characterized by the infiltration of CD1a+CD207+ and CD68+CD1a− clonal mononuclear phagocytes, respectively." (PMID 37673974, 2023). "These histiocytes are positive for S100 and CD68 and negative for CD1a, helping distinguish RDD from other histiocytoses, particularly Langerhans cell histiocytosis." (PMID 40351906, 2025). "Immunohistochemistry further supports its reactive nature, with positivity for CD68 and CD163 indicating macrophage activity, while the absence of langerin and strong CD1a expression helped rule out Langerhans cell histiocytosis." (PMID 41466924, 2025). "ECD cells express the histiocyte marker CD68, CD163, and Factor XIIIa but unlike Langerhans cell histiocytosis do not express CD1a or S100." (PMID 27840753, 2016). "Histopathology confirmed xanthogranulomatous infiltration with foamy histiocytes and Touton giant cells, with immunohistochemistry showing CD68-positive, CD163-positive, CD1a-negative, and S100-negative cells lacking Birbeck granules, consistent with non-Langerhans cell histiocytosis." (PMID 42256999, 2026). "There is a positive immunohistochemistry for the S-100 protein and CD68 marker in RDD, and a negative immunohistochemistry for CD1a, which should be distinguished from lymphoplasmacytic meningioma, plasma cell granuloma, Langerhans cell histiocytosis and Hodgkin lymphoma." (PMID 36596083, 2022).
prostate carcinoma (28 papers, 2002 to 2026). A carcinoma that arises from epithelial cells of the prostate gland. "CD68+ TAMs are present within patients’ prostate cancer skeletal lesions where they are directly associated with woven bone." (PMID 34803925, 2021). "In prostate cancer, increased CD68 expression has been associated with varying outcomes." (PMID 37488490, 2023). "Histiocytic marker like CD68 is a useful staining technique which can differentiate prostatic carcinoma from inflammatory conditions of the prostate." (PMID 41404350, 2026). "Multivariable Cox analysis including prostate cancer-relevant factors (pTNM stage) suggested that CD68/CD206/N1ICD coexpression was an independent indicator of poor PCa prognosis." (PMID 36439868, 2022). "There is currently very limited literature on the contribution of TAMs in the formation of osteolytic lesions, but CD68+ macrophages have been reported within osteolytic lesions of prostate cancer patients." (PMID 34803925, 2021). "The primary analysis of TAMs in 85 prostate carcinomas demonstrated significant increase of the cell profile area and volume density of CD68+ macrophages in cases with higher Gleason score." (PMID 33194645, 2020). "The most abundant double positive pixel class was CD68+/CD163+ and the most abundant triple positive pixel class was CD68+/CD163+/CD206+ (up to 29% of CD68-mask in a case of prostate cancer)." (PMID 30619287, 2018). "In other study with prostate cancer patients, immunization led to recruitment of CD1a+ DCs, CD68+ macrophages, eosinophils, and neutrophils 4 days following inoculation; CD4+ and CD8+ cell affluence increased with immunizations." (PMID 25870600, 2015). "Our study of primary prostate cancer demonstrates an abundant immune cell infiltrate dominated by CD68+ cells with higher density of peritumoral PD-L1+ cells being an independent risk factor for BCR and of peritumoral CD20+ cells being an independent risk factor for metastatic disease." (PMID 39602457, 2024). "Thus, IHC study of 131 Japanese prostate cancer patients detected abundant CD68+ macrophage infiltration in tumor mass in patients with higher serum prostate-specific antigen (PSA) and Gleason score." (PMID 33194645, 2020). "Increased CD68+ macrophage count was observed in metastases from the lymph nodes, liver, bladder, rectum, and seminal vesicles in comparison to the corresponding primary tumors collected from 59 prostate cancer patients from the Norway cohort." (PMID 33194645, 2020). "Thus, a number of studies indicated that higher CD68+ macrophage abundance in tumor tissue reflects aggressive tumor behavior and unfavorable patient outcomes in prostate cancer." (PMID 33194645, 2020). "Several independent investigations confirmed high expression of CD68 in advanced prostate cancer." (PMID 33194645, 2020). "Thus, a significantly higher expression of PD-L1 and VISTA on T cells, CD8+ T cells, and CD68+ macrophages in tumor tissues from prostate cancer patients after anti-CTLA-4 therapy was reported." (PMID 29494517, 2018). "Furthermore, a study involving 93 prostate cancer patients from the Italian cohort identified that high expression of CD68 in primary tumor identified by IHC was an independent predictor of biochemical recurrence (defined as elevation of PSA level) after radical prostatectomy." (PMID 33194645, 2020). "The density, size, and location of tumor infiltrating macrophages in prostate cancer have been showed as powerful predictors of patient outcome, and prostate cancer specimens' harbor increased positive cells expressing the macrophage specific marker CD68 compared to benign glands." (PMID 24772169, 2014). "We demonstrated an abundant immune cell infiltrate within the prostate cancer TME, dominated by CD68+ cells, with substantial numbers of CD8+ and CD4+ T cells." (PMID 39602457, 2024).
prostate carcinoma (continued). "To further support our findings, we analyzed CD68 and CD163 mRNA expression in the TCGA prostate cancer dataset (TCGA-PRAD), which contains 495 PCa samples." (PMID 38189834, 2024). "Then on the order of IL-38+/CD138+ plasmacytes, IL-38+/CD3+ T cell, IL-38+/CD68+ macrophages, and IL-38+/CD20+ B cells, which were 1.80, 1.27, 0.88 and 0.61 per filed in prostate cancer tumour and mesenchyme." (PMID 38779687, 2024). "Increased CD68+ and CD163+ macrophage infiltration was found in a cohort of 60 Chinese prostate cancer patients receiving preoperative Bicalutamide-based ADT." (PMID 33194645, 2020). "CD68-positive cells and P65 were coordinately expressed at moderate to high levels in BPH with chronic inflammation and prostate cancer lesions." (PMID 26010447, 2015). "Indeed, ADT induces prostate cancer infiltration by immune cells, predominantly characterized as CD3+, CD4+, and CD8+ T cells and CD68+ macrophages." (PMID 33284790, 2020). "CD68 is the most reliable marker of macrophages, and PSA is a specific marker of prostate cancer." (PMID 32476259, 2020). "Tumor-free LNs from prostate cancer patients contained more CD68+ and pSTAT-3+ macrophages than LNs from individuals without prostate cancer." (PMID 28472073, 2017). "In sections from human prostate cancer biopsies, many immune cells in the stroma could be seen to express S100A9 and the number of CD68+ macrophages correlated with the number of S100A9+ foci." (PMID 22470535, 2012). "Contrastingly, a prostate cancer trial of neoadjuvant SBRT before radical prostatectomy conducted in only six patients revealed that immune environment was altered 2 weeks after SBRT, with a reduction in CD8+ T cells and an increase in CD68 and CD163 macrophages." (PMID 36358608, 2022). "In the prostate cancer tissue itself, no dendritic cells, 35% of CD45 positive cells, 15% of CD11b positive cells, and no CD68 positive cells were found." (PMID 33921688, 2021). "In the prostate cancer tissue itself, 35% of dendritic cells, 5% of CD45 positive cells, no CD11b positive cells, and 15% of CD68 positive cells were found." (PMID 33921688, 2021). "In the prostate cancer tissue itself, 60% of dendritic cells, 15% of CD45 positive cells, no CD11b positive cells, and 5% of CD68 positive cells were found (for a summary of the results)." (PMID 33921688, 2021).
pancreatic cancer (27 papers, 2012 to 2025). "A recent comprehensive meta-analysis further underscored this association, revealing that pancreatic cancer patients with high numbers of CD68+TAMs had worse overall survival." (PMID 40624025, 2025). "Cathepsin B and L positivity of distinct subsets of tumor-associated macrophages was also confirmed in human pancreatic cancer tissues using immunofluorescence double-staining with CD68 and cathepsin B or L antibodies, respectively." (PMID 32927704, 2020). "Evidence has shown that mice with pancreatic tumor carrying a dominant negative ATG4B mutant displayed a significantly higher number of CD68+ macrophages in the tumors compared to mice carrying wild-type ATG4B." (PMID 38627815, 2024). "In the current study, we aimed to evaluate the diagnostic and prognostic value of CD8, CD68, and VISTA in pancreatic ductal adenocarcinoma (PDAC), a subtype of pancreatic cancer that accounts for the majority of pancreatic cancer cases." (PMID 38357542, 2024). "Specifically, pancreatic cancer tissues characterized by higher Gαi3 expression showed an reduced proportion of macrophages, as evidenced by CD68 and HLA-DR positive staining, indicative of M1-type macrophage presence." (PMID 39349432, 2024). "EpCAM+ cancer cells (PD-L1− or TIM-3−), CD8+ T cells with either PD-1+ or TIM-3+, and CD14+CD68+CD163+TIM-3+ macrophages increased in the MPE of a patient with progressive pancreatic cancer." (PMID 36293034, 2022). "Consistent with the observations of cannibal cells in human pancreatic tumours, Nupr1-depleted Panc-1 cells displayed enhanced ectopic CD68 expression compared to controls." (PMID 22821859, 2012). "To investigate whether SRC‐1 is a key factor in regulating macrophages in PNI in pancreatic cancer, we employed a tissue microarray to analyze the association between SRC‐1 and CD68 expression and the PNI status in tumor tissue." (PMID 40985319, 2025). "Macrophage (CD68+) infiltration in pancreatic tumors was significantly enhanced in Gem/Juz – treated animals, compared with controls (p < 0,001), with significant increases of both, macrophages (CD68+) and for lymphocytes (CD45+), especially at the tumor front." (PMID 39723364, 2024). "Furthermore, CD68+ macrophages and especially CD163+ subpopulations were found to be tightly associated with pancreatic cancer cells." (PMID 30899426, 2019). "In pancreatic cancer, VISTA may induce the immune deficiency microenvironment, and compared to a melanoma, which is sensitive to immunotherapy, the expression of VISTA is higher on CD68+ macrophages in pancreatic cancer." (PMID 35831836, 2022). "We used serial-sectioned pancreatic cancer microarrays for multiple immunofluorescent labeling of major components of the tumor microenvironment, including α-SMA, CD68, CD8, CD20, and CD11C." (PMID 41285728, 2025). "In the current study, CD8, CD68, and VISTA molecules were selected as markers for evaluation in pancreatic cancer due to their well-known roles in regulating immune responses, which are of particular importance in cancer progression." (PMID 38357542, 2024). "The purpose of this study was to investigate the diagnostic and prognostic significance of three markers, CD8, CD68, and VISTA, in pancreatic ductal adenocarcinoma (PDAC), the most common subtype of pancreatic cancer." (PMID 38357542, 2024). "The IHC staining of PDAC tissue samples showed an increased expression of VISTA, CD68, and CD8A in pancreatic cancer tissues." (PMID 38357542, 2024). "The patient-derived pancreatic tumor tissue was chosen according to the expression of markers of tumor cells (CK19) and macrophages (CD68), and AXL detected by immunofluorescence." (PMID 37475048, 2023). "Tumor, stromal and immune ROIs of PDAC were identified on a pancreatic tumor tissue array by PanCK, SMA and CD68 staining respectively." (PMID 33348809, 2020).
pancreatic cancer (continued). "In our present study, Kaplan-Meier survival analysis showed that pancreatic cancer patients with elevated levels of TAMs (indicated by the expression of CD163, CD204, and CD206) or eEF2K, as well as those expressing both CD68 and eEF2K, have poorer overall survival." (PMID 40624025, 2025). "However, there was a significant increase in CD68 expression and a notable reduction in CD8A expression in pancreatic cancer." (PMID 38357542, 2024). "In addition, we performed western blotting of DIAPHs in several pancreatic cancer cell lines and immunohistochemical staining of DIAPH1, DIAPH2, DIAPH3, CD3, CD4, and CD68 in human pancreatic tumor tissues for experimental validation." (PMID 36589226, 2022). "Moreover, SLC40A1 expression positively correlates with the expression of TAM genes (CD68, MRC1, IL10, CSF1, and CSF1R) in pancreatic tumors." (PMID 36333531, 2022). "Interestingly, and consistent with our results, the authors also reported a progressive increase in CD68+ macrophages during IPMN carcinogenesis, thereby highlighting the role of TAMs in the natural history of both biliary and pancreatic cancer." (PMID 36068277, 2022). "Interestingly, it has been observed that M2-like macrophages CD68/CD204+ are more abundant in patients with pancreatic cancer compared with patients with chronic pancreatitis, and their number was correlated with larger tumor size and shorter survival in patients with pancreatic cancer." (PMID 33050070, 2020). "Abundant macrophages and high SRC‐1 expression in CD68+ cells were observed in patients with pancreatic cancer in the “with PNI group,” whereas the expression of SRC‐1 in CD68+ cells was comparatively low in the “without PNI group”." (PMID 40985319, 2025). "In the pancreatic cancer tissue itself, no dendritic cells, 10% of CD45 positive cells, no CD11b positive cells, and no CD68 positive cells were found." (PMID 33921688, 2021). "In the pancreatic cancer tissue itself, 15% of dendritic cells, no CD45 positive cells, no CD11b positive cells, and no CD68 positive cells were found (for a summary of the results, for a representation)." (PMID 33921688, 2021).